PNKP (polynucleotide kinase 3'-phosphatase)
Diseases named in the same sentence as PNKP in open-access papers (continued):
Sharing a sentence is not in itself a finding about the gene and the disease.
PNKP also shares sentences with these, for which no sentence is quoted: neurodevelopmental disorder (5 papers); polyneuropathy (5); Cognitive impairment (4); Intellectual disability (4); cerebellar ataxia (3); Charcot-Marie-Tooth disease (3); colon cancer (3); Dystonia (3); ataxia oculomotor apraxia-4 (2); ataxia telangiectasia (2); colorectal cancer (2); infantile epileptic encephalopathy (2); Machado-Joseph disease (2); Seizure (2); acute myeloid leukemia (1); apraxia (1); Ataxia with Oculomotor Apraxia Type 4 (1); autosomal recessive disease (1); bladder cancer (1); cerebellar degeneration (1); cerebellar hemangioblastoma (1); cerebellar pilocytic astrocytoma (1); dementia (1); developmental and epileptic encephalopathy (1); early-onset epilepsy (1); Friedreich ataxia (1); Gait ataxia (1); hereditary peripheral neuropathy (1); peripheral neuropathy (1); spastic ataxia (1).